CBX3 (chromobox 3)
Diseases named in the same sentence as CBX3 in open-access papers (continued):
Sharing a sentence is not in itself a finding about the gene and the disease.
tumor (continued). "The Ras-related C3 botulinum toxin substrate 1 (RAC1), a small signaling GTPase, has been found to be indirectly regulated by CBX3 during tumor progression, and its gene has been recently found to be amplified in cancer." (PMID 37633946, 2023). "We next studied more in detail the CBX3 copy number (CN) status in tumor samples displaying either diploid or amplified EGFR gene." (PMID 37633946, 2023). "We focused on GBM and lung tumors, as they are currently the only tumor types in which it has been provided evidence of an indirect CBX3-mediated regulation of EGFR and RAC1, respectively." (PMID 37633946, 2023). "Compared to the control group, the CBX3-KD group exhibited suppressed tumor progression, as evidenced by considerably reduced tumor size and weights." (PMID 37674204, 2023). "We next analyzed the RAC1 CN status in the tumor samples, displaying either diploid or amplified CBX3 gene." (PMID 37633946, 2023). "We found that the CBXs relative expression followed a similar trend for both tumor subtypes: CBX3 was the highest among all CBXs, while CBX2 was the lowest." (PMID 36292141, 2022). "CBX3 silencing suppressed tumor growth, and rescuing CBX3 expression attenuated this inhibitory effect." (PMID 35637952, 2022). "We also assessed the link between the CBX3 expression and tumor stage and discovered that the expression of CBX3 exhibited a considerable correlation with tumor stage in ACC, KIRC, LIHC, LUAD, PRAD, and STAD." (PMID 35573019, 2022). "GESA analysis was performed to study the biological value of CBX3 expression in various tumor tissues." (PMID 35573019, 2022). "Next, we examined the differential expression of CBX3 based on the age of patients with each tumor type." (PMID 35573019, 2022). "We analyzed the distribution and expression of CBX3 in different tumor cells and tissues based on the combination of the TCGA, GTEx, and HPA datasets." (PMID 35172803, 2022). "The highest mRNA expressions of CBX3/4/8 were found in grade 2, and the expression level dropped from grade 2 to 3 as the tumor grade increased." (PMID 35969177, 2022). "Normal breast, colon, lung and stomach tissues showed moderate CBX3 IHC staining, whereas tumor tissues depicted strong staining." (PMID 35573019, 2022). "Because of the role of Rac1 in tumor progression, our findings provide a theoretical basis for the development of drugs targeting CBX3 to treat LUAD." (PMID 34785774, 2022). "We demonstrated that significant upregulation of CBX3 and downregulation of CBX7 are consistently associated with enriched cancer stem-cell-like phenotype across distinct tumor types." (PMID 36361869, 2022). "In conclusion, this research provided the pan-cancer analysis of CBX3 and illustrated the differential expression of CBX3 between tumors and non-tumor normal tissues." (PMID 35573019, 2022). "For both assessed RCC subtypes, these three CBXs presented a similar profile: CBX3/6/7 showed the highest rates of genetic alteration, CBX3 mRNA level was upregulated, CBX6/7 associated with tumor stage, and CBX7 also associated with better prognosis." (PMID 36292141, 2022). "Premised on diverse tumors, the CBX3 expression levels generates distinct prognostic outcomes, and the precise function of CBX3 in each of these tumor needs to be further studied." (PMID 35573019, 2022). "The approaches include assessing the link between CBX3 and prognosis of different tumors, immune cell infiltration, micro-satellite instability (MSI), DNA methylation, and tumor mutational burden (TMB)." (PMID 35573019, 2022).
tumor (continued). "The results show that CBX3 is overexpressed in multiple cancers, and significant correlations exist between high expression and adverse prognosis in most tumor patients." (PMID 35172803, 2022). "A distinct relationship was also found between CBX3 expression and TME, including immune infiltration of tumor-infiltrating lymphocytes and cancer-associated fibroblasts, immune score or matrix score, immune checkpoints." (PMID 35172803, 2022). "To investigate the link between the level of CBX3 expression and prognosis, we conducted a survival association analysis that include PFI, DSS, and OS for each tumor." (PMID 35573019, 2022). "Heat maps of immunoactivation, immunosuppression, chemokine and chemokine receptor-related genes showed that most tumor immune-related genes were negatively correlated with CBX3 (P < 0.05) except PCPG, TGCT, THCA and UVM." (PMID 35573019, 2022). "Otherwise, in the pRCC subtype, CBX2, CBX3, CBX7, and CBX8 were deregulated, and CBX2, CBX6, and CBX7 were associated with the tumor stage." (PMID 36292141, 2022). "We employed several bioinformatics methods to explore the potential carcinogenic impact of CBX3 premised on the data sets collected from tumor genome maps, human protein maps, cBioPortal, and genotype tissue expression." (PMID 35573019, 2022). "The results contribute to explaining the role of CBX3 in tumorigenesis from the perspective of clinical tumor samples." (PMID 35172803, 2022). "The CBX3 gene played a tumor-promoting role in PAAD and induced the increased proliferation, migration, and invasion of the PAAD cells." (PMID 35172803, 2022). "We observed that in all 4 tested tumor types and using several distinct stemness quantifiers, the expression of CBX3 is significantly positively, while the level of CBX7 is significantly negatively associated with cancer stemness in TCGA data." (PMID 36361869, 2022). "The S93 locus of CBX3 exhibits a significant difference in phosphorylation level in five primary tumor tissues except for clear cell RCC, compared with normal tissues (all P < 0.05)." (PMID 35172803, 2022). "MRNA expressions of CBX1, CBX2, CBX3, CBX4, and CBX8 were significantly associated with tumor grades." (PMID 35464847, 2022). "Data from multiple databases showed that mRNA and protein expression of CBX3 in tumor tissues was significantly increased." (PMID 35172803, 2022). "Premised on the TCGA data, we also contrasted the expression level of CBX3 among tumor tissues from 18 types of tumors and the matched non-tumor normal samples." (PMID 35573019, 2022). "These outcomes illustrate that the CBX3 expression is strongly correlated with the immune invasion of tumor cells, which impacts the prognosis of patients and provides a novel target for the exploitation of immunosuppressors." (PMID 35573019, 2022). "The mRNA expression levels of CBX3/8 in tumor tissues with different grade were higher than that in normal tissues." (PMID 34117289, 2021). "As the tumor progressed, patients with more advanced tumor grades tended to express higher mRNA expression of CBX3 and CBX4 but lower mRNA expression of CBX1, CBX5, CBX6, and CBX7." (PMID 34395271, 2021). "High expression of CBX3 was found to be strongly associated with a more aggressive subtype of C1, C2, and C6, implicating CBX3 as a potential tumor promoter in EC." (PMID 33463006, 2021). "This indicated there CBX3/5/7 exerted potential effects on the tumor microenvironment and further illustrates its important position within the CBX molecular family." (PMID 34966411, 2021). "Recent studies have shown that CBX3 expression is significantly and inversely correlated with to the abundance of tumor-infiltrating lymphocytes, which influences the efficacy of immunotherapy." (PMID 34966411, 2021). "In our study, CBX3 expression was increased in ccRCC, and the expression of CBX3 was correlated with advanced cancer stage and tumor grade." (PMID 34395271, 2021).
tumor (continued). "Although various studies had been conducted on the mechanism of CBX3 in tumor, the systematic analysis about the upstream regulators and target genes of CBX3 had not been reported yet." (PMID 32894652, 2020). "Similar results were also obtained for CBX2 (tumor specimens: 6.85 ± 0.38; normal ovarian tissues: 1.15 ± 0.20, P < 0.01) and CBX3 (tumor specimens: 8.65 ± 0.31; normal ovarian tissues: 0.54 ± 0.12, P < 0.01) protein expression." (PMID 32742466, 2020). "In contrast to the low CBX3 expression group, the tumor size was significantly larger in the high CBX3 expression group (>5 vs. ≤5 cm, OR = 1.60, 95% CI 1.12-2.28, P = 0.01)." (PMID 33273987, 2020). "CBX3 has been suspected to be responsible of the silencing of tumor suppressor genes and it was demonstrated to be upregulated in many tumors." (PMID 31757200, 2019). "Another study showed a high expression of CBX-3 in various human cancer tissues and suppression of tumor growth of various cancer-derived cell lines following siRNA-mediated knockdown." (PMID 31565104, 2019). "To confirm the correlation between CBX3/HP1γ expression levels in tumor cells and HCC prognosis, we compared OS and recurrence-free survival (RFS) between the high and low CBX3/HP1γ expression groups." (PMID 31375643, 2019). "This resulted in reduced in vitro proliferation of CBX3-overexpressing cells, as well as the anchorage-free growth of tumor cells." (PMID 29903985, 2018). "It was observed that overexpression of CBX3 in KP3L cells promoted the orthotopic growth of tumor cells by time, as evidenced by the quantification of luciferin signal intensity." (PMID 29903985, 2018). "In both datasets, GDS4336 and GDS4103, expression of CBX3 was found significantly elevated in PAAD tissues compared with non-tumor pancreas." (PMID 29903985, 2018). "To predict the mechanism underlying its tumor-promoting activity in PAAD, we first extracted genes that were predicted to have median-to-strong correlations with CBX3 in PAAD." (PMID 29903985, 2018). "Soft agar assay examining the colongenic property of anchorage-independent tumor cells revealed that CBX3 overexpression increased the anchorage-free growth of PAAD cells." (PMID 29903985, 2018). "Taken together, both in vitro and in vivo evidence suggested that CBX3 play a tumor-promoting role in PAAD." (PMID 29903985, 2018). "To further understand the action of CBX3, we performed histological analysis on the Haemotoxylin and Eosin (H&E) stained slides of tumor tissue." (PMID 29903985, 2018). "In PAAD cells, overexpression of CBX3 induced cell proliferation, migration and invasion, and promoted the in vivo tumor growth in nude mice." (PMID 29903985, 2018). "Observation on the size of implanted tumor on pancreas proved that CBX3 overexpression can significantly accelerate tumor growth." (PMID 29903985, 2018). "To understand if CBX3 can promote tumor cell proliferation and invasion in PAAD, we introduced Crispr-cas9 activation plasmid to induce overexpression of CBX3 in PAAD cell line KP3L and PANC-1." (PMID 29903985, 2018). "At week 10, mice reconstituted with wt littermate, Cbx3/HP1γ+/− or Cbx3/HP1γ−/− E17.5 fetal livers were implanted subcutaneously (sc) with NB-9464 tumor cells." (PMID 28220815, 2017). "Treatment of wt tumor-bearing mice with Cbx3/HP1γ-insufficient CD8+ activated T cells alone was successful in inhibiting NB tumor growth." (PMID 28220815, 2017). "At a ratio of 5:1 (5 effector cells to 1 target cell) more CC3 was detected in tumor cells co-cultured with Cbx3/HP1γ-insufficient CD8+ effector T cells compared to control co-cultures." (PMID 28220815, 2017). "The fact that more CD8+ T cells with effector characteristics are recovered from tumors of Cbx3/HP1γ-insufficient mice suggests that Cbx3/HP1γ insufficiency can reinvigorate the effector capacity of CD8+ T cells to control tumor growth." (PMID 28220815, 2017).
tumor (continued). "Tumors from Cbx3/HP1γ-insufficient mice exhibited extensive lymphocytic infiltration, decreased tumor-cell proliferation (less KI-67+ tumor cells) as well as large areas of necrosis, and increased tumor-cell apoptosis (higher levels of CC3)." (PMID 28220815, 2017). "Tumor growth was visible in mice reconstituted with wt fetal livers compared to those receiving Cbx3/HP1γ+/− or Cbx3/HP1γ−/− fetal livers." (PMID 28220815, 2017). "Our results show that treatment with Cbx3/HP1γ-insufficient CD8+ effector T cells alone was sufficient to limit tumor growth in wt tumor-bearing mice." (PMID 28220815, 2017). "Within the tumor microenvironment of Cbx3/HP1γ-insufficient mice or wt mice treated with Cbx3/HP1γ-insufficient CD8+ T cells, we detect an increase of Klrk1/NKG2D+ infiltrating CD8+ effector T cells, a concomitant decrease in CD4+ Treg cells." (PMID 28220815, 2017). "No discernable differences were observed in the frequency of tumor-infiltrating CTLA4+ CD8+ T cells from either wt or Cbx3/HP1γ-insufficient mice." (PMID 28220815, 2017). "Concordantly, tumor volume was reduced in mice reconstituted with Cbx3/HP1γ+/− or Cbx3/HP1γ−/− fetal livers compared to those receiving wt fetal livers." (PMID 28220815, 2017). "We show that Cbx3/HP1γ insufficiency releases the effector capacity of CD8+ T cells to control tumor growth in vivo." (PMID 28220815, 2017). "We show that by targeting the histone reader Cbx3/HP1γ, we can enhance the tumor killing capacity of effector CD8+ T cells." (PMID 29225605, 2017). "Here we find that adoptive transfer of Cbx3/HP1γ-insufficient CD8+ effector T cells alone into wt tumor-bearing mice greatly limits tumor growth." (PMID 28220815, 2017). "We reasoned that Cbx3/HP1γ-insufficient CD8+ T cells armed with heightened killing capacity would be more efficient in controlling tumor growth compared to wt cells." (PMID 28220815, 2017). "Knockdown of CBX3 or blocking K10 Kla significantly inhibited tumor growth." (PMID 39897556, 2025). "For instance, ZEB1 and ZEB2 have been identified as pivotal transcription factors that may influence the transcriptional regulation of CBX3, particularly in tumor cells." (PMID 39272883, 2024). "CBX3 promotes tumor growth and phagocytosis by regulating histone lactylation." (PMID 39545414, 2024). "In addition, since CBX3 has been linked to epigenetic changes such as H3K9me3, which plays a role in regulating the response to DNA damage, we speculate that it could potentially contribute to the resistance of tumor-initiating cells in NSCLC to antineoplastic drugs." (PMID 39272883, 2024). "It is also reported that CBX3 might have an impact on tumor growth by engaging with cell cycle regulators." (PMID 39272883, 2024). "Thus, CBX3 regulates histone lactylation to contribute to tumor growth through both tumor cell-autonomous and phagocytosis evasion mechanisms." (PMID 39545414, 2024). "CBX3 knockdown increases phagocytosis in vivo and prolongs survival of tumor-bearing mice." (PMID 39545414, 2024). "We next investigated the effects of CBX3 on tumor growth in vivo." (PMID 39545414, 2024). "Interestingly, the in vivo inhibition of CBX3 results in a reduction in tumor size and an extension of the survival period in mice with KRASG12D-induced LUAD." (PMID 39272883, 2024). "This interaction suggests a significant role for CBX3 in oncogenic processes, where it might be part of broader regulatory mechanisms driving tumor progression." (PMID 39272883, 2024). "Given the connection among histone lactylation, microglial/macrophage phagocytosis, and CBX3, we tested to determine whether CBX3 regulates phagocytosis of tumor cells." (PMID 39545414, 2024).
tumor (continued). "Cbx3 knockdown inhibited in vivo tumor growth and increased survival of tumor-bearing mice." (PMID 39545414, 2024). "Furthermore, we identified an interdependent relationship among CBX3, tumor immune disorders, and the PI3K pathway." (PMID 37674204, 2023). "We found that, whereas in the 85–95% of the cases EGFR diploidy was associated with the CBX3 diploidy, the tumors displaying gene amplification of EGFR locus show a dramatic enrichment in the frequency of both low (gain; 10–90% of tumor specimens) and high (amplification; 5–80%) increase of CBX3 CN." (PMID 37633946, 2023). "Furthermore, the analysis of the CN status of such samples revealed that the specimens with multiple copies of EGFR gene have a strong tendency to display low gain increase in CBX3 CN (80% of the samples compared to 5% of tumor with EGFR gene diploid)." (PMID 37633946, 2023). "Moreover, the tumor samples with amplified RAC1 display a drastic increase of either low gain or high-grade amplification of CBX3 gene." (PMID 37633946, 2023). "Interestingly, the analysis of the correlation between mRNA levels and the CN status also revealed that the cancer samples with amplified EGFR show a statistically significant increase of CBX3 mRNA expression regardless the tumor tissue of origin." (PMID 37633946, 2023). "Interestingly, in none of the diverse cancer types analyzed, including TCGA Pan Cancer Atlas samples, we observed an increase of CBX3 transcripts compared to tumor samples which are diploid for either EGFR or RAC1." (PMID 37633946, 2023). "In the CBX3-high expression group, increased in PIK3R6 expression levels were associated with score increases (EstimateScore, StromalScore, ImmuneScore) and decreases in tumor purity." (PMID 37674204, 2023). "In short, these results strongly suggest that CBX3 plays a vital role in tumor immunity." (PMID 35172803, 2022). "This research provides an in-depth understanding of the function of CBX3 in tumor immunotherapy." (PMID 35573019, 2022). "We explored the potential oncogenic roles of CBX3 in mRNA and protein levels based on the diverse databases, including the expression, the correlation with prognosis, tumor microenvironment (TME), DNA methylation, protein phosphorylation and enrichment analysis across all TCGA tumors." (PMID 35172803, 2022). "In addition, the finding showed that CBX3 expression was correlated with tumor immunity and clinical survival." (PMID 35172803, 2022). "However, deep studies focusing on CBX3 expression and tumor immune microenvironment should be researched to provide a therapeutic strategy based on the immune." (PMID 35172803, 2022). "Our data clearly demonstrate yet-unrecognized association of high CBX3 expression with cancer stem cell-like phenotype of solid tumors, regardless of the tumor type." (PMID 36361869, 2022). "However, knockdown of CBX3 diminished the tumor growth-promoting effect induced by CSE or nicotine treatment in vivo." (PMID 34785774, 2022). "The outcomes also indicate that CBX3 has a critical function in tumor immunity and might serve as an imperative biomarker." (PMID 35573019, 2022). "In addition, CBX3 expression showed a promising ability to distinguish tumor tissue from normal tissue, with AUC values > 0.9 in eight tumors, including BLCA, BRCA, HNSC, COAD, LIHC, LUAD, LUSC, and STAD." (PMID 35573019, 2022). "CBX3 in most tumor tissues has a higher expression level, compared with that in normal tissue." (PMID 35172803, 2022). "Our research uncovered a significant association between cancer stemness and an elevated expression of HP1 group of CBX family members, especially—CBX3, where the association was robust and universal regardless of the tumor type." (PMID 36361869, 2022).